SEL1L (SEL1L adaptor subunit of SYVN1 ubiquitin ligase)
Diseases named in the same sentence as SEL1L in open-access papers (continued):
Sharing a sentence is not in itself a finding about the gene and the disease.
renal disease (1 paper, 2015). "There was attenuation of association of SNPs near RRM1|STIM1 and STON2|SEL1L after adjustment (although still significant at p<0.05, unadjusted for multiple comparisons), suggesting that these SNPs have effects on SCDA levels mediated through these clinical factors, in particular renal disease." (PMID 26540294, 2015).
SEL1L also shares sentences with these, for which no sentence is quoted: cerebellar ataxia (6 papers); developmental delay (4); microcephaly (3); HCMV infection (2); Intellectual disability (2); metabolic disorders (2); adenocarcinoma (1); colorectal cancer (1); colorectal tumors (1); diffuse large B-cell lymphoma (1); hippocampal atrophy (1); Hyperglycemia (1); influenza (1); Insulin resistance (1); pancreatitis (1); Polyuria (1); retinal degeneration (1); Tremor (1); type 1 diabetes (1).